IL18 (interleukin 18)
Diseases named in the same sentence as IL18 in open-access papers (continued):
Sharing a sentence is not in itself a finding about the gene and the disease.
Insulin resistance (continued). "IL-18 levels were related to several indices of general and visceral adiposity and insulin resistance in the PCOS group where age, waist circumference, and fasting insulinemia most closely explain serum amounts of this proinflammatory biomarker." (PMID 35263047, 2022). "Upon activation of NLRP3, a large amount of proinflammatory cytokines including IL-1β and IL-18 are secreted, aggravating glucose intolerance and insulin resistance." (PMID 34948026, 2021). "IL-1β and IL-18 contribute to insulin resistance and islet β-cell damage in T2DM; they are classic pro-inflammatory cytokines of the IL-1 family." (PMID 34737846, 2021). "In this study, IL-18 receptor−/− mice exhibited inflammation, weight gain, lipid deposition, and attenuated AMPK signaling in skeletal muscles, which indicated that IL-18 was involved in metabolic homeostasis, inflammation, and insulin resistance." (PMID 33546399, 2021). "Hyperglycemia is accompanied by an up-regulated expression of TNF-α, interleukin (IL)-1β, IL-6, and IL-18, which contribute to insulin resistance by both JNK and the IKKβ/NF-kβ pathway." (PMID 32431669, 2020). "Numerous researches have showed that the activation of NLRP3 inflammasome and the release of downstream IL-1β and IL-18 can promote the process of liver inflammation, triglyceride deposition, and insulin resistance during the NAFLD/NASH." (PMID 31827504, 2019). "We observed that in type 2 diabetic rats, which demonstrated insulin resistance, the level of IL-18 was significantly lower than in control healthy rats." (PMID 31771099, 2019). "IL-18 has been found to be involved in the regulation of metabolic homeostasis and insulin resistance; however, IL-18 has been found to be necessary for the prevention of hyperphagia in IL-18–deficient mice models." (PMID 31835423, 2019). "A previous study has demonstrated that IL-18-knockout (Il18−/−) mice have a remarkably increased body weight accompanied by high insulin resistance and dyslipidemia." (PMID 30453990, 2018). "Obese individuals have increased levels of circulating IL-18 that are markedly correlated with metabolic syndrome and insulin resistance." (PMID 30619282, 2018). "In their study, IL-18 serum level had a direct positive relationship with BMI, testosterone, and insulin resistance." (PMID 28042549, 2017). "The mRNA expression of IL18 is also increased in obese individuals, and this increase is correlated with insulin resistance." (PMID 27482295, 2016). "Serum IL-18 levels were elevated in women with PCOS compared to controls (p = 0.003) and clearly associated with insulin resistance." (PMID 27747236, 2016). "Further, NLRP3 upregulates the pool of proinflammatory cytokines such as IL-1β, IL-18, and IFNγ and promotes insulin resistance in M1 macrophages." (PMID 24744784, 2014). "Recent investigation showed a strong and clear correlation between IL-18 and insulin resistance in T2DM subjects and also in non-T2DM subjects." (PMID 24282409, 2013). "The major findings from this study are the effects of variation within IL-18 using combined haplotypes analysis, on insulin levels and estimates of insulin resistance." (PMID 20227263, 2011). "Further analysis demonstrated a relationship between IL-18 gene promoter polymorphisms and PCOS insulin resistance (IR)." (PMID 20964873, 2010). "Furthermore, IL18 levels in serum or plasma are negatively correlated with carbohydrate tolerance and positively related to insulin resistance." (PMID 38139000, 2023). "Considering the relationship between IL-18 and insulin resistance observed by other authors, we first aimed at elucidating whether this relationship held true in this study cohort." (PMID 37049621, 2023). "Considering the relationship between dietary fatty acid intake and IL-18 levels, it was next evaluated whether the quality of fatty acid intake was also related to insulin resistance." (PMID 37049621, 2023).
Insulin resistance (continued). "In light of this, IL-18, alongside TNF-α, may be implicated in the pathogenesis of insulin resistance." (PMID 37049621, 2023). "IL-1β and IL-18 also contribute to adipose tissue inflammation and insulin resistance, and the significant reduction in their mRNA levels following CGWE treatment indicates its potential to mitigate these inflammatory pathways and improve metabolic health in obese individuals." (PMID 37571229, 2023). "In particular, this study provides further support to the pathophysiological relevance of inflammation in this process, highlighting the role of IL-18 as an inflammatory biomarker linking a shift in dietary lipid intake towards saturated fatty acid and insulin resistance." (PMID 37049621, 2023). "This study aims to evaluate whether the quality of lipid intake impacts upon IL-18 plasma levels and the implications on insulin resistance computed by the homeostatic model assessment for insulin resistance (HOMA-IR)." (PMID 37049621, 2023). "Interleukin-18 (IL-18) was discovered in 1989 and has since been found to be expressed in skeletal muscle, be increased in plasma following exercise, to increase fatty acid oxidation in isolated mouse soleus muscle, and to reduce insulin resistance in mice." (PMID 36479347, 2022). "In addition, circulating IL-18 levels were positively correlated with the Homeostasis Model Assessment of Insulin Resistance (HOMA-IR) index and glucose intolerance, independently of BMI or age." (PMID 36313762, 2022). "In a previous study, gene expression of IL-18 was up regulated due to insulin resistance." (PMID 35317787, 2022). "Interestingly, a recent study revealed that targeted disruption of SHP2 in macrophages had a protective effect towards HFD-induced insulin resistance, which was assigned to its role in repressing IL18 production." (PMID 36140242, 2022). "Moreover, SHP2 inhibition correlated with an increase in IL18 plasma levels, which contributed to alleviate insulin resistance." (PMID 36140242, 2022). "Yet, IL18 reduces bodyweight gain and insulin resistance and increases energy homeostasis." (PMID 36482059, 2022). "Osteopontin and IL18 are related to insulin resistance in obese subjects." (PMID 34948944, 2021). "Overall, these findings suggest that IL-18 induces inflammatory responses that may lead to insulin resistance and T2DM development." (PMID 33546399, 2021). "For example, interleukin-1 β (IL-1β) and interleukin-18 (IL-18) are continuously increased and their receptor expression is up-regulated under chronic hyperglycemia, which can lead to pancreatic β cell apoptosis, functional decline and insulin resistance." (PMID 34531719, 2021). "Compared with Il18+/+ mice, Il18−/− mice developed kidney failure in their youth-6 weeks of age, but the condition was observed to improve as the mice aged, even though dyslipidemia, arteriosclerosis, and higher insulin resistance occurred." (PMID 29514661, 2018). "Mice lacking whole-body IL-18 signalling are prone to develop weight gain and insulin resistance, a phenotype which is associated with impaired fat oxidation and ectopic skeletal muscle lipid deposition." (PMID 29342149, 2018). "Interestingly enough, these cytokines have been implicated in insulin resistance (TNF-α, IL-6, and IL-1β), atherosclerotic plaque destabilization (IL-18), and future cardiovascular events (IL-6, IL-18, IL-1β, and TNF-α)." (PMID 27034691, 2016). "Moreover, overexpression of IL-18 aggravated insulin resistance in a rat model of metabolic syndrome." (PMID 24733068, 2014). "In this particular scenario, the relationship between OPN and IL-18 could be very crucial in development of insulin resistance in obese individuals." (PMID 23675517, 2013). "Brun JM etal reported that plasma IL-18 was associated with changes in insulin resistance but not with BMI." (PMID 24349077, 2013).
Insulin resistance (continued). "In summary, we show for the first time that plasma, PBMCs and adipose tissue OPN and IL-18 levels are simultaneously increased and correlate with each other in overweight/obese individuals which may trigger the development of insulin resistance." (PMID 23675517, 2013). "The insulin resistance in these mice is corrected by exogenous recombinant IL-18." (PMID 24115947, 2013). "Adipocytes from obese individuals produce higher levels of IL-18 compared with lean individuals and higher circulating IL-18 levels were observed in obese individuals and those with a high body mass index (BMI), insulin resistance, hypertriglyceridemia, and metabolic syndrome." (PMID 22531046, 2012). "Obviously, whether mechanistic link exists between circulating IL-18 and skeletal muscle insulin resistance in pathogenesis of cardio-metabolic disorders needs to be elucidated further." (PMID 21437204, 2011). "Nevertheless, IL-18 levels have been have been consistently associated with insulin resistance measured by the homeostasis model assessment (HOMA) and studies in humans and il18−/− mice suggest a possible role for IL-18 in insulin sensitivity and energy homeostasis." (PMID 20227263, 2011). "Interestingly, in a rat model with the metabolic syndrome, IL-18 overexpression aggravated insulin resistance, increased vascular inflammation and promoted remodeling by enhanced infiltration of macrophages and increased medial thickness in the aortic wall." (PMID 20331890, 2010). "A high plasmatic concentration of IL18 is correlated with insulin resistance and body mass index." (PMID 19664222, 2009). "Despite this, an increase in the circulating levels of this cytokine has been shown to predict the onset of T2DM, which, independently of whether it may have a causal role in triggering insulin resistance, supports the role of IL-18 as a plausible predictor of insulin resistance." (PMID 37049621, 2023). "However, direct evidence on the causal role of IL-18 in the pathogenesis of insulin resistance are still lacking." (PMID 37049621, 2023). "However, considering that dietary fatty acids were unable to directly predict insulin resistance, we investigated whether they represented predictors of IL-18 plasma levels." (PMID 37049621, 2023). "It is known that some cytokines such as IL-18 may not be affected by weight loss but with alterations in insulin resistance." (PMID 36232744, 2022). "In addition, it has been shown that IL-18 mRNA and plasma IL-18 correlated with insulin resistance, suggesting that training-induced reduction in IL-18 expression may be a contributing mechanism to improve insulin sensitivity after training." (PMID 26788518, 2016). "ASC is necessary for assembly of inflammasome complexes, which activates the inflammatory cytokines IL1 and IL18 from their propeptides in response to saturated fatty acid overload, thereby linking lipid metabolism and inflammation and promoting the development of insulin resistance in T2DM." (PMID 24086498, 2013). "Mesenchymal stem cell was found to alleviate insulin resistance in T2DM rats by suppressing NLRP3 inflammasome-mediated inflammation and expression of IL-1β and IL-18." (PMID 38987672, 2024). "Furthermore, considering the central role of insulin resistance in the pathogenesis of metabolic syndrome, it was next investigated whether IL-18 circulating levels differed between study participants affected by metabolic syndrome and their metabolically healthy counterparts." (PMID 37049621, 2023). "Using a cross-sectional design, this study confirmed that IL-18 correlated positively with insulin resistance and individuals with a HOMA-IR ≥ 2.5 displayed higher circulating IL-18 levels compared with their insulin-sensitive counterparts." (PMID 37049621, 2023). "Twelve-week combined aerobic and resistance exercise was shown to lower insulin resistance index, expressions of TLR4, NF-κB p65 in monocytes, and serum IL-18 level in diabetic patients." (PMID 34948026, 2021).
Insulin resistance (continued). "Although plasma IL-18 was reported to be higher in obese subjects and correlated with insulin resistance (HOMA), IL-18 release by adipose tissue explants was reduced in obese women." (PMID 24918199, 2014). "Importantly, obese individuals with a combined OPN/IL-18 elevation may be at a greater risk for developing insulin resistance as compared with non-obese population." (PMID 23675517, 2013). "This strengthens the argument that IL-18 is not merely a marker of inflammation, but an active contributor to β-cell failure, insulin resistance, and long-term diabetic complications." (PMID 40804870, 2025). "Furthermore, LrB can reduce inflammation and insulin resistance in individuals with PCOS by inhibiting NLRP3, Caspase-1, TNF-α, IL-6, IL-1β, and IL-18 and increasing the expressions of GPR120, LKB1, and AMPK." (PMID 39456928, 2024). "Despite this, IL-18 circulating levels, but not dietary fatty acid quality, predicted insulin resistance." (PMID 37049621, 2023). "The activation of the NLRP3 inflammasome could enhance the expression of IL-1β, IL-18, and interferonγ (IFNγ), while it inhibits IRS-1/PI3K/AKT signaling, thereby leading to insulin resistance." (PMID 36187801, 2022). "It’s concentration is increased in PCOS patients regardless of presence of insulin resistance and obesity, however, obese women with hyperinsulinemia have even higher concentrations of IL-18." (PMID 33917519, 2021). "Specific to insulin resistance observed in T2DM is the involvement of the NLR family pyrin domain containing 3 (NLRP3) inflammasome, which activates inflammatory cytokines IL-1β and IL-18 and can lead to more severe insulin resistance." (PMID 33086602, 2020). "Mice lacking IL-18 or the IL-18 receptor and therefore impaired IL-18 signalling become obese and display hyperinsulinemia, insulin resistance and dyslipidemia." (PMID 29342149, 2018). "Active caspase-1 can eventually process IL-1β and IL-18 precursors, serving as enhancer of multiple proinflammatory pathways including NF-κB, mitogen-activated protein kinase (MAPK), IFNγ, chemokines, and ROS and also promoting insulin resistance." (PMID 24744784, 2014). "Studies have reported strong evidence that suggests YKL-40, α-HB, soluble CD36, leptin, resistin, IL-18, RBP4, and chemerin could be new biomarkers for the pathogenesis of insulin resistance and endothelial dysfunction in T2DM patients." (PMID 24282409, 2013). "The general mechanisms of IL-18 in the context of insulin resistance involve lineal effects of IL-18 on insulin signaling with or without tumor necrosis factor-α (TNF-α) stimulation in tissues and a secondary response of IL-18 to insulin resistance." (PMID 24282409, 2013). "Our findings, together with previous findings, suggest that Il-18, as a pro-inflammatory factor, does not contribute to HF-induced insulin resistance at the expression level." (PMID 20307313, 2010). "Elevated plasma interleukin-18 is a marker of insulin-resistance in type 2 diabetic and non-diabetic humans." (PMID 18570670, 2008). "High blood IL-18 levels in T2DM may indicate IL-18 resistance, akin to insulin resistance." (PMID 40243151, 2025). "Thus, the aim of this study was to investigate how saturated and unsaturated fatty acids and their ratios affect IL-18 circulating levels in a cohort of non-diabetic individuals and the repercussions on insulin resistance." (PMID 37049621, 2023). "Regarding the mechanism of higher blood glucose levels and insulin resistance in Il18−/− mice, the phosphorylation of signal transducer and activator of transcription 3 (STAT3) was impaired in the liver and was recovered by the administration of recombinant-IL18 (rIL18)." (PMID 38139000, 2023). "The data reported herein provide evidence on the role of dietary fatty acids on the regulation of IL-18 circulating levels and further support the tight relationship between this pro-inflammatory cytokine and insulin resistance in a cohort of non-diabetic individuals." (PMID 37049621, 2023).
Insulin resistance (continued). "Furthermore, Il18−/− mice exhibited higher blood glucose and lipid levels, insulin resistance, non-alcoholic fatty liver disease (NAFLD), and non-alcoholic steatohepatitis (NASH) with aging." (PMID 38139000, 2023). "However, none of the other variables correlating positively with IL-18 circulating levels, including dietary fatty acids, were able to predict insulin resistance." (PMID 37049621, 2023). "However, IL-18 appears to act as an indicator for insulin resistance but not for β-cell malfunction." (PMID 24282409, 2013). "In addition, Se may reduce insulin resistance through inhibiting the activity and the production of inflammatory cytokines including tumour necrosis factor-a (TNF-a), nuclear factor-kappa B (NF-κB) and interleukin (IL-1 and IL-18)." (PMID 28380029, 2017). "Elevated IL-18 concentrations have been observed in PCOS patients, regardless of insulin resistance and obesity status." (PMID 40181376, 2025). "From a mechanistic perspective, the relationship between AGE intake and insulin resistance does not appear to be related to NLRP3 inflammasome activation which, in turn, is pivotal for IL-18 production." (PMID 40263184, 2025). "Thus, previous studies have suggested that insulin resistance resolution could be a factor driving the reduction in systemic inflammation by showing significant reductions in HOMA-IR before considerable reductions in the levels of IL-6, MCP-1, IL-18, TNF-α19,43,44." (PMID 34108550, 2021).